ALCAM (activated leukocyte cell adhesion molecule)
Diseases named in the same sentence as ALCAM in open-access papers (continued):
Sharing a sentence is not in itself a finding about the gene and the disease.
uveal melanoma (3 papers, 2012 to 2019). A melanoma derived from melanocytes of the uveal tract. "Our results have implicated ALCAM as a regulator of cadherin-based adherens junctions in uveal melanoma cells." (PMID 22745734, 2012). "We describe a correlation between ALCAM expression and motility in a gap closure assay in uveal melanoma cells." (PMID 22745734, 2012). "Previous microarray analysis of two uveal melanoma cell lines identified ALCAM as one of the genes most upregulated in invasive cells (line MUM-2B) compared to non-invasive cells (line MUM-2C)." (PMID 22745734, 2012). "Here, we sought to address this by utilizing a number of defined uveal melanoma cell lines with high or low ALCAM levels, and testing the effects of manipulating these levels on cell motility, invasiveness, and adhesion using multiple measures." (PMID 22745734, 2012). "We next sought to determine how silencing ALCAM impacts invasive capacity of MUM-2B uveal melanoma cells." (PMID 22745734, 2012). "Together, these data demonstrate that ALCAM expression positively correlates with cell motility in uveal melanoma cell lines." (PMID 22745734, 2012). "If ALCAM expression is necessary for motility and invasiveness in the MUM-2B uveal melanoma cell line, is ALCAM expression sufficient to increase motility and confer invasiveness in the normally ALCAM-negative MUM-2C line?" (PMID 22745734, 2012). "To begin to address the role of ALCAM in tumor cell behavior, we assembled a panel of five uveal melanoma cell line stocks: OCM-1A, MUM-2B, MUM-2C, C918, and M619." (PMID 22745734, 2012). "Studies describing ALCAM function in uveal melanoma, the most common form of primary intraocular cancer, are lacking." (PMID 22745734, 2012). "We find that, across several uveal melanoma cell lines, ALCAM expression positively correlates with cell motility." (PMID 22745734, 2012). "Together with our analysis of sh5 silenced cells, these data suggest that ALCAM expression is both necessary and sufficient to promote the recruitment of N-cadherin and ß-catenin to form adherens junctions in uveal melanoma cells." (PMID 22745734, 2012). "The cutaneous-derived BLM cell line, being devoid of cadherin expression, might not be subject to the same changes in signaling induced by decreasing ALCAM-ALCAM interactions as would our uveal melanoma cell lines." (PMID 22745734, 2012). "To better understand how ALCAM might regulate cancer cell behavior, we utilized a panel of defined uveal melanoma cell lines with high or low ALCAM levels, and directly tested the effects of manipulating these levels on cell motility, invasiveness, and adhesion using multiple assays." (PMID 22745734, 2012). "Given that ALCAM expression can modulate N-cadherin localization at cell-cell junctions, we can envision the following possibilities as to how ALCAM status might influence the migratory and invasive properties of uveal melanoma cell lines." (PMID 22745734, 2012). "As expected from our previous results with the 2C-ALC cell line MMP-2 activity was not increased in 2C-ALC compared to parental MUM-2C; again, this suggests that ALCAM is necessary, but not sufficient, for an invasive cell phenotype in uveal melanoma." (PMID 22745734, 2012). "To determine whether ALCAM regulates uveal melanoma cell behavior, we began by knocking down ALCAM levels in MUM-2B cells, which normally express high levels of ALCAM." (PMID 22745734, 2012). "Thus, our experiments demonstrate that ALCAM expression is necessary for cell motility and invasiveness in MUM-2B uveal melanoma cells." (PMID 22745734, 2012). "We were not, however, able to co-immunoprecipitate ALCAM with N-cadherin in uveal melanoma cells, suggesting that any interaction may not be direct or may be sensitive to our lysis conditions." (PMID 22745734, 2012).
viral infection (3 papers, 2017 to 2020). "Expression of these genes is associated with movement (MMP9, SPP1, ALCAM, and others), viral infection (APOC1, LGALS3, CD63, and others), and recruitment of phagocytes (APOE, CHI3L1, LGALS3, and others)." (PMID 32723919, 2020). "Taken together, these data show that type 1 Tregs arising during chronic viral infection suppress effector Th1 cells by engaging ALCAM." (PMID 33375121, 2020). "Here, we further extended this finding and functionally link expression of the CD85k ligand ALCAM with the ability of Th1 cells to be efficiently suppressed by type 1 Tregs in the setting of a chronic viral infection." (PMID 33375121, 2020). "In the context of a full virus infection, E4orf6 is required for ALCAM reduction." (PMID 28631589, 2017). "Given that CD85k+ Tregs are induced and in the case of chronic LCMV infection even maintained during viral infection, we hypothesized that the interaction of CD85k on Tregs with its ligand ALCAM on effector cells could limit the effector T cell response during persistent infection." (PMID 33375121, 2020). "When cells were treated with 20 μM MG132, EPHA2 and ALCAM the protein levels in Ad5-infected cells remained comparable to those of mock-infected cells, whereas, surprisingly, PTPRF levels were decreased in MG132-treated cells, even without viral infection." (PMID 28631589, 2017).
acute myeloid leukemia (2 papers, 2024). Acute myeloid leukemia (AML) is a group of neoplasms arising from precursor cells committed to the myeloid cell-line differentiation. "Many previous studies have shown that ALCAM is linked to the development of several types of solid cancer and acute myeloid leukemia." (PMID 38560563, 2024). "In more recent findings, LILRB4 was shown to bind CD166 (activated leukocyte adhesion molecule, ALCAM) and serum apolipoprotein E (APOE), which mediate tumor cell growth and acute myeloid leukemia, respectively." (PMID 38397424, 2024).
Alzheimer disease (2 papers, 2022). A progressive, neurodegenerative disease characterized by loss of function and death of nerve cells in several areas of the brain leading to loss of cognitive function such as memory and language. "In a nutshell, these findings revealed ALCAM and VCAM-1 as reliable indicators of Alzheimer’s disease." (PMID 36685605, 2022).
chronic pancreatitis (2 papers, 2012 to 2019). A chronic inflammatory process causing damage and fibrosis of the pancreatic parenchyma. "Tissue specimens and blood sera of patients with PAC (n = 264 and n = 116, respectively) and the sera of 115 patients with chronic pancreatitis (CP) were analyzed via ALCAM immunohistochemistry and s-ALCAM ELISA tests." (PMID 22745698, 2012).
COVID-19 (2 papers, 2023 to 2024). A disease caused by infection with severe acute respiratory syndrome coronavirus 2. "Besides PARP9, the three genes KRT8, SEC14L1, and ALCAM have also been linked to COVID-19." (PMID 38666857, 2024). "Another biomarker identified within our study to be elevated in severe COVID-19, but not reported before, is ALCAM (Activated Leukocyte Cell Adhesion Molecule, CD166), which plays a role in transmigration of monocytes across pulmonary endothelium and in T-cell activation." (PMID 37041310, 2023).
cutaneous melanoma (2 papers, 2012 to 2015). A primary melanoma arising from atypical melanocytes in the skin. "Low expression of ALCAM in regional lymph node metastases is a feature associated with unfavorable prognosis in patients with cutaneous melanoma." (PMID 26134500, 2015). "The aim of the study was to assess the expression and intracellular localization of ALCAM in primary skin melanomas and metastatic lesions from regional lymph nodes." (PMID 26134500, 2015). "Formalin-fixed paraffin-embedded tissue specimens from 104 primary cutaneous melanomas and 16 regional lymph nodes metastases were studied for the expression of ALCAM measured by immunohistochemistry." (PMID 26134500, 2015). "The aim of the study was to assess the expression and intracellular localization of ALCAM in 104 primary skin melanomas and 16 metastatic lesions from regional lymph nodes." (PMID 26134500, 2015). "An amino terminal-truncated (dominant negative) form of ALCAM was transfected into cutaneous melanoma cells, and was found to diminish cell clustering and enhance both motility in vitro and the transition from primary tumor to tissue invasion in vivo." (PMID 22745734, 2012). "The role of ALCAM in cutaneous melanoma was first addressed directly by the laboratory of Guido Swart." (PMID 22745734, 2012). "For example, initial studies described a positive correlation between ALCAM expression and metastatic capacity or progression of cutaneous melanoma." (PMID 22745734, 2012). "High ALCAM expression in cancer cells of the primary tumor (IRS ≥8) is closely correlated with unfavorable prognosis in cutaneous melanoma patients as regards cancer specific overall survival and particularly disease free survival (P = 0.001 and P < 0.001, respectively)." (PMID 26134500, 2015). "It appeared that the disruption of homophilic ALCAM contacts thus resulted in increased metastatic potential in cutaneous melanoma cell lines; this was, however, in contrast to previous expression data that predicted ALCAM would promote invasion and metastasis." (PMID 22745734, 2012).
dementia (2 papers, 2019 to 2022). Loss of intellectual abilities interfering with an individual's social and occupational functions. "Our study highlights the changes and potential contributions of several chemokines (CXCL1, CCL3, CXCL5, CXCL6, CCL3, CCL19), interleukins (IL8, IL6-RA, IL18-BP), and other immune markers (OSM, ALCAM, OPG, CHIT1, YKL-40, STAMBP, MMP-9, MMP-10) in the prodromal and dementia phases of AD." (PMID 31694701, 2019).
gastric tumour (2 papers, 2017 to 2023). "To monitor the impact of ALCAM alteration on the interaction of cancer and mesothelial cells, we performed both ECIS assay (that records the dynamic interaction between tumour and mesothelial cells) and DiI-based assay (measuring pancreatic/gastric tumour-endothelial interaction)." (PMID 36614319, 2023).
Hypercholesterolemia (2 papers, 2016 to 2019). An increased concentration of cholesterol in the blood. "In vitro studies have shown that sALCAM is involved in ALCAM-dependent and –independent immune responses upon inflammatory stimulation and that endothelial expression of ALCAM is induced by hypercholesterolemia." (PMID 27737658, 2016).
laryngeal squamous cell carcinoma (2 papers, 2020 to 2022). A squamous cell carcinoma that arises from the larynx. "In a variety of cancers such as laryngeal squamous cell carcinoma, ALCAM overexpression can be used as an important prognostic marker of disease progression." (PMID 36482887, 2022). "ALCAM gene overexpression in laryngeal squamous cell carcinoma was poor." (PMID 36482887, 2022).
mastitis (2 papers, 2013 to 2021). Inflammation of breast tissue during lactation or postpartum due to an obstructed duct or infection. "In addition, in a study of milk somatic cells which had been challenged with Staphylococcus epidermidis or Staphylococcus aureus, ALCAM was shown to be over-expressed in the milk somatic cells of a mastitis-resistant line of sheep in comparison with a mastitis-susceptible line." (PMID 24223582, 2013). "It has been shown that ALCAM is overexpressed in the somatic milk cells of a mastitis-resistant sheep line compared to a mastitis-sensitive line." (PMID 34940759, 2021). "Therefore, ALCAM seems a plausible candidate gene to be involved in mastitis resistance." (PMID 24223582, 2013).
medulloblastoma (2 papers, 2020 to 2021). A malignant, invasive embryonal neoplasm arising from the cerebellum. "The study has found that ALCAM positivity was significantly linked to the status of CNNTB1 and the presence of nuclear beta-catenin in the medulloblastoma tumours." (PMID 34680335, 2021). "In a cohort of 45 medulloblastoma tumours, ALCAM positivity was observed in only 18% of the tumours, with positive tumours mainly seen in the WNT group and the SHH group of the patients." (PMID 34680335, 2021).
papillary thyroid carcinoma (2 papers, 2011 to 2021). "Through proteomic characterization of ALCAM expression in the human papillary thyroid carcinoma cell line TPC-1, we identified the presence of a full-length membrane-associated isoform in cell lysate and of soluble ALCAM isoforms in conditioned medium." (PMID 21364949, 2011).
preeclampsia (2 papers, 2018 to 2023). Preeclampsia is a hypertensive disorder of pregnancy that is characterized by new-onset hypertension with proteinuria presenting after 20 weeks of gestation, and depending on mild or severe forms may initially present with severe headache, visual disturbances, and hyperreflexia. "Reduced PPARG inhibited the histone demethylase KDM3B from demethylating ALCAM, thereby reducing ALCAM expression, which eventually leads to preeclampsia." (PMID 36894952, 2023). "The first is activated leukocyte cell adhesion molecule (ALCAM), which is a TE-expressed protein in human placentae whose expression is diminished during preeclampsia." (PMID 30305020, 2018).
prostate tumor (2 papers, 2012 to 2019). "Elevated THY1 (CD90) expression has previously been reported within prostate tumor stroma, but ALCAM (CD166) has not been previously investigated." (PMID 31061140, 2019).
rheumatoid arthritis (2 papers, 2022 to 2024). A chronic, systemic autoimmune disorder characterized by inflammation in the synovial membranes and articular surfaces. "In rheumatoid arthritis (RA), both known CD6 ligands, ALCAM and CD318, are known to participate in adhesion of T cells to fibroblast-like synoviocytes (FLS) derived from RA synovial tissue." (PMID 36275816, 2022).
salivary gland tumor (2 papers, 2017 to 2020). "In a similar way, ALCAM protein level was described as potential biomarkers for predicting tumor behavior and prognosis of salivary gland tumor in Iranian patients." (PMID 32085563, 2020).
thyroid tumor (2 papers, 2011 to 2021). A benign or malignant neoplasm affecting the thyroid gland. "Total ALCAM in poorly differential thyroid tumours was found to be markedly lower than those with well/moderately differentiated tumours, and the reduction was associated with distant metastasis and shortened survival (6 years vs. 13.7 years, low vs. high cytoplasmic ALCAM, respectively)." (PMID 34680335, 2021). "In this respect, the possibility that the high levels of ALCAM expression in thyroid tumors may indicate a reprogramming in transcriptional activity due the loss TTF-1 may deserve further investigation." (PMID 21364949, 2011). "Here we documented high levels of ALCAM expression in human thyroid tumors and cell lines." (PMID 21364949, 2011). "In view of the role of ALCAM dynamics in some human tumors, we studied its expression in thyroid tumors, which had not been previously explored." (PMID 21364949, 2011).
type 1 diabetes (2 papers, 2017 to 2020). "Recently, a urinary proteome profiling study identified several increased urinary proteins including ALCAM in type 1 diabetes patients as compared to their healthy siblings, alluding to its potential role in the pathogenesis of intermittent hyperglycemia and inflammation." (PMID 32460901, 2020).
acute coronary syndrome (1 paper, 2020). Signs and symptoms related to acute ischemia of the myocardium secondary to coronary artery disease. "High serum levels of ALCAM were independently associated with an increased risk of cardiovascular death in acute coronary syndrome." (PMID 32849633, 2020).
Adamantinomatous Craniopharyngioma (1 paper, 2020). A craniopharyngioma consisting of broad strands, cords and bridges of a multistratified squamous epithelium with peripheral palisading of nuclei. "Interestingly, it has been recently reported that there is a strong correlation between nuclear staining of β-catenin and ALCAM levels in adamantinomatous craniopharyngioma, which is closely related to the Wnt signal pathway." (PMID 33270750, 2020).
adenovirus infection (1 paper, 2017). "However, additional studies will be required to explain in detail how adenovirus infection modulates overall ALCAM abundance." (PMID 28631589, 2017).
allergic asthma (1 paper, 2023). A asthma with a basis in a pathological type I hypersensitivity reaction. "Intranasal treatment with a polyclonal anti-ALCAM antibody was previously shown to reduce inflammatory symptoms in an OVA-induced model of allergic asthma." (PMID 37514028, 2023). "ALCAM has previously been brought forward as a target for allergic asthma." (PMID 37514028, 2023). "Finally, we tested two of the newly developed antibody fragments as well as the parent antibody IF8-Fc in vivo in a mouse model of allergic asthma to further validate ALCAM as a disease target upon topical application." (PMID 37514028, 2023).
anemia (1 paper, 2022). A reduction in the number of red blood cells, the amount of hemoglobin, and/or the volume of packed red blood cells. "Logistic regression analysis of CD166/ALCAM haplotype association with anti-nuclear antibodies (ANA), cytopenia, anemia, lymphopenia, peripheral nervous system (PNS) ESSDAI activity, and pSS susceptibility." (PMID 35372412, 2022). "The CD166/ALCAM rs6437585C-rs579565G-rs1044243T haplotype was associated with increased ANA positivity, ESSDAI PNS activity, and hematologic cytopenias, such as anemia and lymphopenia." (PMID 35372412, 2022).
B cell lymphomas (1 paper, 2021). "Of the screened four genes (ALCAM, CD22, CASP1, and CISH), CD22 is a sialic acid-binding immunoglobulin-like lectin (Siglec) that is highly expressed on B cell lymphomas and is a validated target for antibody and nanoparticle-based therapeutics on non-Hodgkin lymphoma." (PMID 34026619, 2021).
carcinoma in situ (1 paper, 2017). "Urine ALCAM remained an independent predictor of OS after accounting for treatment with Bacillus Calmette-Guerin, carcinoma in situ, lymph-node dissection, lymphovascular invasion, urine creatinine, and adjuvant chemotherapy (HR, 1.10; 95% CI, 1.02–1.19; P = 0.011)." (PMID 27894096, 2017). "In non-invasive carcinoma in situ, the expansion of the urothelium led to an increase in ALCAM positive cells with no increase in signal intensity (CIS)." (PMID 27894096, 2017).
cardiac conduction disease (1 paper, 2021). "Mice deficient in NCAM-1, but not CNTN2 or ALCAM, exhibited defects in PC gene expression and VCS patterning, as well as cardiac conduction disease." (PMID 34100064, 2021).
chordoma (1 paper, 2021). Chordomas are rare malignant tumors arising from embryonic remnants of the notochord in axial skeleton. "In another study to search for proteomic changes in chordoma, ALCAM was identified to be one of the lead upregulated proteins in recurrent chordoma compared with the primary chordoma tumours." (PMID 34680335, 2021).
chronic kidney disease (1 paper, 2020). Impairment of the renal function secondary to chronic kidney damage persisting for three or more months. "However, our goal in this study was not to validate the diagnostic role of urinary ALCAM in differentiating LN from other chronic kidney diseases." (PMID 32460901, 2020).
corneal disease (1 paper, 2019). "Since corneal allograft rejection is an important medical condition that also involves (lymph)angiogenesis, DC migration and T cell activation, we investigated the therapeutic potential of ALCAM blockade in murine corneal disease." (PMID 31031759, 2019).
disc degeneration (1 paper, 2022). "However, within these processes, only a few genes were commonly upregulated in human cluster D2 and N153S tissues, including BIRC3, CFD, RSAD2, and ALCAM – none of which are considered inflammatory hallmarks of disc degeneration." (PMID 35769461, 2022).
dysplasia (1 paper, 2013). A usually neoplastic transformation of the cell, associated with altered architectural tissue patterns. "Significant loss of membranous E-cadherin and β-catenin expression was observed from normal, hyperplasia, dysplasia to OSCCs (ptrend <0.001); and correlated with cytoplasmic ALCAM accumulation in OSCCs (p = 0.006)." (PMID 23840677, 2013).